SIPA1 (signal-induced proliferation-associated 1)
Description:
GTPase activator for the nuclear Ras-related regulatory proteins Rap1 and Rap2 in vitro, converting them to the putatively inactive GDP-bound state. Affects cell cycle progression (By similarity).
Synonyms: SPA1
Tractability: Antibody: UniProt places it where antibodies can reach, with high confidence; the Human Protein Atlas places it where antibodies can reach. PROTAC: ubiquitination databases record sites on it; its protein half-life has been measured.
Gene: Protein-coding gene on chromosome 11 (65,638,091 to 65,650,930, forward strand). Ensembl gene ENSG00000213445.
Subcellular location: Nucleus; Cytoplasm, perinuclear region; Endomembrane system
Subcellular location (Human Protein Atlas): Nucleoli; Golgi apparatus; Nucleoplasm; Plasma membrane
Pathways (Reactome):
Immune System: Rap1 signalling
Gene Ontology:
Molecular function: GTPase activator activity; protein binding
Biological process: adaptive immune response; cytoskeleton organization; intracellular signal transduction; negative regulation of cell adhesion; negative regulation of cell cycle; negative regulation of cell growth; signal transduction; cellular response to water deprivation; regulation of small GTPase mediated signal transduction
Cellular component: nucleus; cytosol; endomembrane system; perinuclear region of cytoplasm; protein-containing complex
Genetic constraint (gnomAD): Loss-of-function variants: 53 observed, 71.2 expected, observed/expected ratio (o/e) 0.74, 90% interval 0.6 to 0.94. The synonymous counts are far from expectation, so gnomAD's model fits this gene poorly and the ratio says little. Missense variants: 1,348 observed, 1,244.2 expected, observed/expected ratio (o/e) 1.08, 90% interval 1.03 to 1.13. Synonymous variants: 681 observed, 559.72 expected, observed/expected ratio (o/e) 1.22, 90% interval 1.14 to 1.3.
Homologues: Orthologues: chimpanzee SIPA1 (100% identical), macaque SIPA1 (99% identical), pig SIPA1 (91% identical), dog SIPA1 (90% identical), guinea pig SIPA1 (90% identical), mouse Sipa1 (90% identical), rat Sipa1 (89% identical), tropical clawed frog sipa1 (46% identical), zebrafish sipa1 (42% identical), Drosophila melanogaster RapGAP1 (17% identical), Caenorhabditis elegans F53A10.2 (15% identical). Paralogues in human: SIPA1L2 (43% identical), SIPA1L1 (42% identical), SIPA1L3 (42% identical), GARNL3 (21% identical), RAP1GAP2 (17% identical), RAP1GAP (17% identical).
Diseases named in the same sentence as SIPA1 in open-access papers:
SIPA1 is named in the same sentence as 36 diseases in open-access papers, as found by Europe PMC text mining. Sharing a sentence is not in itself a finding about the gene and the disease. The quoted sentences say what the papers report.
breast carcinoma (18 papers, 2006 to 2025). "Signal-induced proliferation-associated protein 1 (SIPA1) promotes the secretion of exosomes enriched with myosin heavy chain 9 (MYH9) from breast cancer cells." (PMID 40564894, 2025). "We then demonstrated that HIF-2α (encoded by EPAS1) was directly regulated by SIPA1 in breast cancer cells." (PMID 35096814, 2021). "SIPA1, signal-induced proliferation-associated protein 1, promotes breast cancer cell invasion, migration and metastasis." (PMID 32193333, 2020). "The finding prompted us to compare the expression patterns of SIPA1 with two molecules, vimentin and E-cadherin, which are closely associated with epithelial and mesenchymal features, in TCGA breast cancer patient samples." (PMID 32193333, 2020). "We will also discuss the association of two genes, Brd4 and Sipa1 (signal-induced proliferation-associated 1), with mammary tumor progression in both the mouse and the human." (PMID 22295248, 2012). "A recent study also reported that germline SNPs of the SIPA1 gene are associated with major clinical characteristics, such as estrogen receptor status and lymph node metastasis in human breast cancer." (PMID 19765277, 2009). "Signal-induced proliferation-associated 1 was first identified as a potential breast cancer metastasis modulator in the mouse model." (PMID 19765277, 2009). "This, as well as previous functional work, adds support to the involvement of the SIPA1 gene and its SNPs in breast cancer susceptibility." (PMID 19765277, 2009). "The protein expression level of SIPA1 in the mouse model has been linked to breast cancer metastasis propensity as increased levels lead to increased metastasis and decreased levels lead to a decreased amount of lung metastasis." (PMID 19765277, 2009). "In this preliminary study we observed strong associations between the three SIPA1 SNPs and indicators of aggressive breast cancer in this population." (PMID 16563182, 2006). "This again highlights the deleterious effect that SIPA1 germline variation has on prognosis in primary breast carcinoma and implies that variant forms of this gene are associated with more aggressive disease forms." (PMID 16563182, 2006). "Our previous work using a mouse mammary tumor model has shown that metastatic efficiency is modulated by the GTPase-activating protein encoded by Sipa1 ('signal-induced proliferation-associated gene 1')." (PMID 16563182, 2006). "Moreover, EVs derived from the breast cancer with high expression of signal-induced proliferation-associated 1 (SIPA1) enhance macrophage migration toward the tumor site." (PMID 40443670, 2025). "The high expression of signal-induced proliferation-associated 1 (SIPA1) in breast cancer could aggravate cancer cell metastasis, but how the tumour microenvironment is involved in this incident is unknown." (PMID 35453742, 2022). "In addition, it is reported that EVs from breast cancer cells (MDA-MB-231) expressing high levels of signal-induced proliferation-associated 1 (SIPA1) promote the migration of macrophages to tumor tissue." (PMID 36405712, 2022). "Signal-induced proliferation-associated 1 (SIPA1), a member of Rap1GAP family, is aberrantly expressed in breast cancer, colorectal cancer, melanoma and prostate cancer cells, participating in the regulation of tumor cell proliferation, adhesion, invasion and metastasis." (PMID 35096814, 2021). "In human solid tumors, a polymorphism in the SIPA1 gene causing higher RapGAP activity was associated with high metastatic potential of breast cancer, and SIPA1 expression was found to positively correlate with disease progression and metastasis in human prostate cancer." (PMID 22535842, 2012). "Therefore, this study investigated the potential relationship of SIPA1 and human breast cancer incidence by a germline SNP genotype frequency association study in a case-control Caucasian cohort in Queensland, Australia." (PMID 19765277, 2009).
breast carcinoma (continued). "Results indicated significance with SIPA1 SNP rs3741378; the CC genotype was more frequently observed in the breast cancer group compared to the disease-free control group, indicating the variant C allele was associated with increased breast cancer incidence." (PMID 19765277, 2009). "This suggests that SIPA1 may be involved in different stages of breast carcinogenesis and since this study replicates a previous study of the associated SNP, it implicates variants of the SIPA1 gene as playing a potential role in breast cancer." (PMID 19765277, 2009). "Subsequent human studies demonstrated that SIPA1 polymorphisms are associated with metastatic cancer and poor outcome in breast cancer, validating the utility of the highly metastatic polyoma middle-T (PyMT) transgenic mouse model to identify relevant human metastasis modifiers." (PMID 18081427, 2007). "We hypothesized that polymorphisms or haplotypes within key regulatory or coding elements of the human gene encoding SIPA1, located on chromosome 11q13.3, are positively correlated with the presence of metastases in breast cancer patients." (PMID 16563182, 2006). "The aim of this study was to determine whether single nucleotide polymorphisms (SNPs) within the human SIPA1 gene are associated with metastasis and other disease characteristics in breast cancer." (PMID 16563182, 2006). "Therefore, the mechanism causing breast cancer cell adhesion, migration, and invasion can be explained by SIPA1, which may be achieved by regulating the ITGB1/FAK/Akt-MMP9 signaling pathway." (PMID 36230738, 2022). "Studies of human breast cancer have suggested that SIPA1 germline polymorphisms are associated with aggressive disease behavior and with indicators of poor prognosis, suggesting that Sipa1 may play an important role in establishing metastatic susceptibility in humans as well as in mice." (PMID 22295248, 2012). "This study confirmed that SIPA1 functioned as a TF to regulate cell junctional organization and extracellular matrix organization and to promote breast cancer progression." (PMID 37500797, 2023). "The proportion of SIPA1-positive cells in breast cancer cells ( > 50%) was higher than that in normal mammary epithelial cells ( < 10%), indicating that SIPA1 was aberrantly expressed in breast cancer cells, when compared to normal mammary epithelial cells." (PMID 37500797, 2023). "The SIPA1 positive breast cancer cells account for more than 90% of SIPA1-positive cells, while breast cancer cells were just account for 63.11% of all cells." (PMID 37500797, 2023). "SIPA1 was previously shown to localize in the nuclei of metastatic breast cancer cells in the presence of fibronectin or fetal bovine serum (FBS)." (PMID 37500797, 2023). "Aggressive lung metastasis took place in mice transplanted with SIPA1-expressing breast cancer cells, whereas the invasiveness was significantly attenuated by SIPA1-knockdown." (PMID 37500797, 2023). "It was most likely that breast cancer cells with a high level of SIPA1 expression recruited macrophages into the tumour microenvironment." (PMID 35453742, 2022). "We revealed that SIPA1 promoted the transcription of MYH9, which encodes myosin-9, and up-regulated the expression level of myosin-9 in breast cancer cells and their EVs." (PMID 35453742, 2022). "In this study, we set out to clarify the effect of high expression of SIPA1 in breast cancer cells on macrophage recruitment in the tumour microenvironment." (PMID 35453742, 2022). "Current research has also found that SIPA1 protein can prove breast cancer cell stemness by targeting the CD44 gene, and enhance aerobic glycolysis of cancer cells by targeting the EPAS1 gene to promote cancer cell metastasis." (PMID 36230738, 2022). "We analysed the components of EVs derived from the SIPA1-highly expressing breast cancer cells and found that myosin-9 was selectively present in the EVs." (PMID 35453742, 2022).
breast carcinoma (continued). "Here, we first demonstrated that macrophages infiltrated tumour tissues in breast cancer patients with a high level of SIPA1 expression." (PMID 35453742, 2022). "We revealed that LINC01615 is regulated by the transcription factor SIPA1 in promoting breast cancer cell malignancy." (PMID 36230738, 2022). "The expression of LINC01615 is regulated by the transcriptional activator SIPA1, thereby promoting carcinogenesis in breast cancer cells." (PMID 36230738, 2022). "Survival analysis showed that breast cancer patients with high expression of SIPA1 and MYH9 molecules had worse relapse-free survival (p = 0.028)." (PMID 35453742, 2022). "It has been reported that the accumulation of TAMs contributes to tumour metastasis; hence, we examined the effect of EVs derived from SIPA1-expressing breast cancer cells on the metastasis of orthotopic tumours." (PMID 35453742, 2022). "The results reveal a new mechanism that SIPA1 regulates breast cancer cell EMT and then promotes metastasis by up-regulating the expression of LINC01615, which provides a new way to clarify the process of metastasis in cancer." (PMID 36230738, 2022). "In conclusion, SIPA1 in breast cancer cells promoted MYH9 transcription and up-regulated the expression of myosin-9." (PMID 35453742, 2022). "We found that SIPA1 up-regulated myosin-9 levels in breast cancer cells as well as in EVs by binding to the MYH9 gene promoter." (PMID 35453742, 2022). "Signal-induced proliferation-associated 1 (SIPA1) is markedly expressed in MDA-MB-231, a highly metastatic human breast cancer cell line." (PMID 35453742, 2022). "In summary, we confirmed the regulatory effect of SIPA1 on LINC01615 in breast cancer cell lines, which is ultimately reflected in cell migration and invasion and tumor metastasis in vivo." (PMID 36230738, 2022). "This study shows that SIPA1 regulates one of the downstream pathways of breast cancer metastasis; namely, SIPA1 can regulate the expression of the corresponding lncRNA to regulate metastasis." (PMID 36230738, 2022). "Previous studies have shown that SIPA1 can promote metastasis by regulating adhesion, drug resistance, and stem ability of breast cancer cells." (PMID 36230738, 2022). "SIPA1 is involved in many aspects of malignancy, such as breast cancer cell metastasis, maintenance of stemness, and drug resistance." (PMID 35453742, 2022). "SIPA1 knocked down in breast cancer cells significantly reduced FAK and Akt phosphorylation and inhibited MMP9 extracellular secretion through the integrin-mediated FAK/AKT-MMP9 signaling pathway." (PMID 36230738, 2022). "The macrophages markedly infiltrated the breast cancer tissues expressing a high level of SIPA1, whereas only a few macrophages were observed in the tissues expressing a low level of SIPA1." (PMID 35453742, 2022). "Here, we demonstrated that aberrant expression of signal-induced proliferation-associated 1 (SIPA1) enhanced aerobic glycolysis and altered the main source of ATP production from oxidative phosphorylation to glycolysis in breast cancer cells." (PMID 35096814, 2021). "The present findings indicate a potential target for the development of therapeutics against breast cancers with dysregulated SIPA1 expression." (PMID 35096814, 2021). "The mRNA levels of EPAS1 as well as TGFB1, VEGFA and CA9, were confirmed to be positively correlated with those of SIPA1 in these two pairs of breast cancer cells and BT549, another TNBC cell line." (PMID 35096814, 2021). "We then compared the invasiveness of the breast cancer cells with SIPA1 or HIF-2α knockdown with that of parental cells by using a transwell assay." (PMID 35096814, 2021). "In the present study, we showed that metabolic transformation to decreased glycolysis and increased mitochondrial oxidative phosphorylation induced by SIPA1 knockdown led to poor metastatic properties of breast cancer cells." (PMID 35096814, 2021).
breast carcinoma (continued). "The findings strongly suggested that the SIPA1/HIF-2α axis is critical for aerobic glycolysis and pivotal for metastasis in breast cancers highly expressing SIPA1." (PMID 35096814, 2021). "The potential of SIPA1 in regulating TJs has also been confirmed in breast cancer and prostate cancer in the host laboratory." (PMID 33917539, 2021). "In the present study, we demonstrated that SIPA1 was aberrantly expressed in some breast cancer cells, especially in TNBC cells, and promoted aerobic glycolysis, leading to tumor invasion and metastasis in vivo." (PMID 35096814, 2021). "It was previously demonstrated that SIPA1 up-regulated the promoter activity of certain target genes in breast cancer cells." (PMID 35096814, 2021). "We also found that blocking aerobic glycolysis by either knocking down SIPA1 expression or oxamate treatment led to the suppression of tumor metastasis of breast cancer cells both in vitro and in vivo." (PMID 35096814, 2021). "In fact, SIPA1 knockdown breast cancer cells exhibited impaired growth in xenografted mice, whereas rapid proliferation was observed in vitro under normoxia." (PMID 35096814, 2021). "A linear regression analysis revealed a negative correlation between SIPA1 and E-cadherin expression in breast cancer tissues (*P<0.001) and a positive correlation between SIPA1 and vimentin expression (*P<0.001)." (PMID 32193333, 2020). "Overexpression of SIPA1 has been identified in several types of cancer, including colorectal and breast cancer." (PMID 32699531, 2020). "The results suggest that EMT is suppressed in breast cancer cells with a low level of SIPA1 expression." (PMID 32193333, 2020). "We thus examined the relationship between the mRNA expression levels of TGFB1 (TGFβ), CTNNB1 (β-catenin), SNAI1, SNAI2 and ZEB1 and those of Sipa1 in TCGA breast cancer patient samples." (PMID 32193333, 2020). "5-Aza-2′-deoxycytidine (5-Aza-CdR), a DNA methyltransferase inhibitor, promoted the expression of Sipa1 in the MCF7 breast cancer cells with a low level of SIPA1 expression." (PMID 32193333, 2020). "By contrast, relatively high levels of SIPA1 protein were observed in the other three breast cancer cell lines (MDA-MB-231, BT549 and SK-BR-3) with high migration capacity." (PMID 32193333, 2020). "We also examined the relationship between the Sipa1 methylation status and the mRNA expression level in the TCGA breast cancer dataset." (PMID 32193333, 2020). "Our previous work demonstrated that nuclear-localized SIPA1 interacted with the promoter of the integrin β1 gene and induced its transcription, possibly promoting the breast cancer invasion." (PMID 32193333, 2020). "They provided the evidences that BRD4 long isoform reduced metastasis, however short isoform enhanced metastasis in breast cancer through interactions with the metastasis susceptibility protein RRP1B and SIPA1." (PMID 25603177, 2015). "Immunohistochemical staining of the breast cancer TMAs from the Human Protein Atlas also showed predominantly cytoplasmic SIPA1, however staining at the nuclear periphery was observed in many cancer cells." (PMID 24260471, 2013). "While it showed association with hormonal receptor status in breast cancer group in a previous pilot study, this exonic missense SNP (Ser (S) to Phe (F)) changes a hydrophilic residue (S) to a hydrophobic residue (F) and may significantly alter the protein functions of SIPA1 in breast tumourgenesis." (PMID 19765277, 2009). "The novel breast cancer gene SIPA1 was originally identified as a candidate gene for breast cancer metastasis from mouse studies." (PMID 19765277, 2009). "The novel breast carcinogenesis gene SIPA1 has important molecular functions as a breast cancer metastasis modulator." (PMID 19765277, 2009).